KRAS (KRas proto-oncogene, GTPase)
Diseases named in the same sentence as KRAS in open-access papers (continued):
Sharing a sentence is not in itself a finding about the gene and the disease.
cancer (continued). "In the mice, dTAGV-1 administration led to robust and durable degradation of KRASG12V, along with pronounced inhibition of downstream signaling, consistent with previous findings from studies using KRAS inhibitors in murine cancer models." (PMID 39718828, 2024). "In this therapy, CD8+ T-cells engineered to specifically target antigenic mutant KRAS fragments displayed by cancer cells are infused into patients." (PMID 38668053, 2024). "This approach yielded 9 distinct clusters, each encapsulating a theme of importance in the context of KRAS-induced cancer immunotherapy." (PMID 39252322, 2024). "Our findings offer strong evidence for the promise of developing degraders targeting mutant KRAS in cancer and also establish an in vivo platform for drug target discovery and validation." (PMID 39718828, 2024). "In fact, substantial research has reported an increase in PI3K pathway activity following the inhibition of the p44/42 MAPK pathway in KRAS-mutant cancers." (PMID 38409090, 2024). "In preclinical models, ASOs targeting the ESE induced PTC formation and decreased KRAS Q61K activity as well as similar mutations in NRAS and HRAS mutant cancers." (PMID 39316554, 2024). "RAC1 is an important cancer driver downstream of KRAS and its ablation in mouse models delayed the onset of precancerous lesions and led to an inability to sustain precancer progression to PDAC." (PMID 38712822, 2024). "Our data suggest that KRAS inhibition affects myeloid cell maturation and highlights the need for combining KRAS cancer-targeted therapy with myeloid activation to enhance and prolong antitumor effects." (PMID 38727236, 2024). "Herein, while initial responses to CDK9‐targeted therapies are observed in vitro across various KRAS‐mutant cancer types, their efficacy is far from satisfactory in nude mouse xenograft models." (PMID 39254172, 2024). "KRAS is the predominant isoform that is mutated in cancer, including in more than 90% of cases of PDAC, a leading cause of cancer mortality in the USA4 and globally." (PMID 38588697, 2024). "Our findings suggest that ICBs, TCR-T, and cancer vaccines represent the forefront of innovative approaches capable of transforming the management of KRAS-mutant tumors." (PMID 39252322, 2024). "We used different machine learning models to identify new promising hits from the ZINC database against the KRAS G12D cancer drug target." (PMID 38794122, 2024). "Suppression of PD-L1 and KRAS led to a slowdown of the cell cycle in the G0/G1 phase and reduced migration, increased sensitivity to chemotherapy and triggered apoptosis of cancer cells." (PMID 39201772, 2024). "The Catalogue Of Somatic Mutations In Cancer (COSMIC) shows that about 25% of all cancers carry mutations in RAS genes, and KRAS is responsible for about 70% of these mutations (COSMIC, v.95)." (PMID 37833074, 2024). "Sotorasib (development code name AMG 510), a covalent inhibitor targeting this mutation, has demonstrated potential in providing a more prolonged and specific interaction with the KRAS protein, a crucial approach in cancer therapy." (PMID 39043787, 2024). "Here, we investigated the sensitivity of KRAS-mutant cancers to SUMOylation inhibition by TAK-981 and identified a potential predictive biomarker." (PMID 38992694, 2024).
cancer (continued). "KRAS G12C inhibitors are a significant breakthrough in the treatment of advanced NSCLC and other cancers harboring KRAS mutations." (PMID 38397927, 2024). "Most newly developed immunotherapeutics for treating KRAS-related cancers are ICBs, with PD-1 and PD-L1 being prime examples." (PMID 39252322, 2024). "C3 and its active fragment C3a, downstream effectors of classical complement activation mediated by C1q/C1s/C1r, were time‐dependently increased following AZD4573 treatment, as well as PD‐L1 in KRAS‐mutant cancer cells." (PMID 39254172, 2024). "Taken together, our data suggest that inhibition of YAP/TAZ synergizes with KRAS G12C inhibitors to induce robust apoptosis in cancer cells via upregulating the expression of proapoptotic genes such as BCL2L11, BMF, and PUMA." (PMID 39704172, 2024). "From the data, we observed that both MSLN & CEA antigens have enrichment terms with respect to the extracellular-related functions and are implicated in several cancers including PDAC and CRC in which the KRAS is highly mutated." (PMID 39453574, 2024). "Our method also identified KRAS-MAP3K2 as a potential pan-cancer synthetic lethality pair by comparing KRAS pWT cell lines with KRAS mutant cell lines in the CRISPR screen." (PMID 37863651, 2024). "Sotorasib and adagrasib have similar mechanisms of action through covalent binding of the cysteine 12 site within the KRAS G12C protein, rendering KRAS inactive and preventing cell proliferation, effectively halting cancer cell progression." (PMID 38672653, 2024). "These include proteins expressed or secreted by pancreatic cancer cells, the desmoplastic stroma characterized by cancer-associated fibroblasts and pancreatic stellate cells, the low TMB typical of PDAC, as well as the role of mutant KRAS." (PMID 39518557, 2024). "Considering the recent discovery of selectively potent KRAS mutant inhibitors, it is worthy to investigate the combination of KRAS inhibitors with ferroptosis inducers in cancer therapy." (PMID 38908072, 2024). "ACA-28 and its lead compound ACAGT-007a were shown to induce apoptosis in cancer cell lines with different oncogenic mutations, ranging from HER2, BRAF, NRAS, and KRAS." (PMID 38500550, 2024). "Subcutaneous (SC) tumors of varying sizes were developed using cancer cell lines for KRAS G12C/S/V/D/A, G13D, and Q61H in NSG (NOD/Shi-scid/IL-2Rγnull) mice." (PMID 38938409, 2024). "Here, we provide data that supports the role of neutrophil-specific CXCR2 expression in enhancing colorectal liver metastasis in KRAS mutant cancer." (PMID 38358352, 2024). "The crosstalk between KRAS and Hippo signaling pathways in cancer is complex and involves multiple mechanisms." (PMID 39431199, 2024). "In contrast, genes such as APC, KRAS, CTNNB1, and GATA6, showed a higher mutation frequency in precancerous lesions than in advanced cancer." (PMID 39554798, 2024). "We next clarified the underlying mechanism by which HOXC10 downregulation suppressed KRAS-mutant cancer growth and bone metastasis by utilizing genome-wide RNA-seq analysis." (PMID 39191757, 2024). "The three main RAS genes that are frequently mutated in human cancers include Harvey rat sarcoma viral oncogene homolog (HRAS), Kirsten rat sarcoma viral oncogene homolog (KRAS), and Neuroblastoma ras viral oncogene homolog (NRAS)." (PMID 38982514, 2024). "Understanding the interplay between MYC dysregulation and KRASi resistance offers insights into co-targeting strategies to potentially enhance treatment efficacy in KRAS-driven cancers." (PMID 39164274, 2024).
cancer (continued). "The passage conducted a scientometric analysis on a subset of 16,609 publications in correlation with KRAS-related cancer over the period from 2013 to 2022." (PMID 38706597, 2024). "Despite extensive studying of KRAS’s significance in many cancers, developing effective treatments has remained difficult." (PMID 39001451, 2024). "Numerous studies have demonstrated the role of MYC as a crucial stress adaptation factor in KRAS-driven cancers." (PMID 39164274, 2024). "The constitutive activation of the MAPK pathway as a result of KRAS mutations has led to the use of trametinib as a potential therapeutic option to treat KRAS-mutant cancers." (PMID 38643157, 2024). "Targeting KRAS is considered one of the optimal strategies to combat KRAS-driven tumors and improve advanced cancer patients’ outcomes." (PMID 38216551, 2024). "We further revealed that inhibitors targeting the Src, Mcl‐1, STAT3, BRD4, p300, PLK1, or class I HDACs significantly enhanced CDK9i‐induced cell death in various KRAS‐mutant cancers." (PMID 39254172, 2024). "Heterogenous responses of KRAS-mutant cancers towards MEK inhibitors in the clinic has been widely reported." (PMID 38409090, 2024). "Abnormal KRAS signaling in cancer can also be identified through high-level amplification of the KRAS gene." (PMID 38576709, 2024). "Inhibition of YAP/TAZ strikingly increases the sensitivity of KRAS G12C–mutant cancer cells to KRAS G12C inhibitors." (PMID 39704172, 2024). "In 1982, the RAS genes HRAS and KRAS were discovered as the first human cancer genes, with KRAS later identified as one of the most frequently mutated oncogenes." (PMID 39732595, 2024). "The top 10 articles with the most local citation scores in the research of KRAS-related cancer during 2013 to 2022." (PMID 38706597, 2024). "Oleuropein exhibits a more variable profile; it can either decrease levels of tumor suppressors like SIRT1 or alter oncogene expressions such as KRAS and mTOR, depending on the cancer type." (PMID 39203892, 2024). "It is known that oncogene allelic imbalance is a frequent event in cancer cells, known to impact key oncogene loci such as KRAS and BRAF1." (PMID 38168062, 2024). "Next, we analyzed the expression of HOXC10 in the primary and metastasis subgroups of pan-KRAS-mutant cancer using The Cancer Genome Atlas (TCGA) datasets." (PMID 39191757, 2024). "We therefore continued with a 2D proliferation analysis for synergismin five KRAS mutant and dependent cancer cell lineswith diverse levels of PDE6D and PRKG2 dependencies." (PMID 38758695, 2024). "The development of resistance to KRAS G12C inhibitors remains a major obstacle in treating KRAS-driven cancers." (PMID 39704172, 2024). "In these cancers, ABI1 expression is also positively correlated with KRAS mutation and is proposed to be an early marker for KRAS mutagenesis in hyperplastic polyps." (PMID 39354505, 2024). "Approximately one-third of all human cancers, including pancreatic, lung, colorectal, and ovarian cancers, are driven by mutations in the RAS oncogenes (KRAS, HRAS, and NRAS), which are upstream molecules in the MAPK/ERK signalling pathway." (PMID 39120319, 2024). "Pathway enrichment analysis revealed that these genes with splicing events were primarily involved in the cell cycle and other cancer‐related pathways, such as KRAS signaling and heme metabolism." (PMID 39036344, 2024).
cancer (continued). "In humans, there are three RAS isoforms: KRAS, NRAS, and HRAS; among these, the KRAS isoform is the most frequently mutated in cancers (>85%)." (PMID 38473821, 2024). "Applications with high doses of VC have been proposed for KRAS mutant cancer treatment related to the glucose-dependent absorption of the oxidized form of VC, dehydroascorbate, by cancer cells." (PMID 38473779, 2024). "CRC and NSCLC are the dominant types of cancer clinically investigated for the combination treatments of KRAS G12C, but clinical trials have included a minority of patients with other types of cancer." (PMID 38756650, 2024). "Cancer pathologies are often orchestrated by various metabolites, and KRAS mutant tumors are especially exposed to dramatically increased levels of lactic acid." (PMID 38216551, 2024). "KRAS, a well-recognized oncogene across various cancers, activates key pathways such as MAPK and PI3K, leading to increased cell proliferation, survival, and migration." (PMID 38794205, 2024). "KRAS-mutant cancers have been difficult to treat via drugs due to the small size of K-Ras and its lack of binding sites." (PMID 39720730, 2024). "The downregulated pathways included several, such as the KRAS signaling pathway, the EMT pathway, and the calcium signaling pathway, all of which are strongly associated with cancer progression." (PMID 39555091, 2024). "The most prevalent post-translational modification within the GTPase core domain of NRAS and KRAS is ubiquitination at lysine 128 (K128), which is significantly decreased in cancer samples compared to normal tissue." (PMID 38858602, 2024). "Efforts to target mutant KRAS signaling in cancer have advanced tremendously, with multiple KRASG12C-specific inhibitors in clinical or preclinical development, but the rapid development of resistance limits progression-free survival." (PMID 39103541, 2024). "KRAS signaling pathway inhibition has been a major focus of research in cancer therapy, and drugs targeting different pathway components are currently being evaluated in clinical trials." (PMID 38481800, 2024). "Next, we examined the sensitivity of TAK-981 to multiple KRAS-mutant human and mouse cancer cell lines using a cell viability assay." (PMID 38992694, 2024). "In contrast, mutations in three other genes of the KRAS pathway, BRAF, SOS1, and NF1, were significantly more common in CDX2-suppressed cancers." (PMID 39452477, 2024). "The D-VC and L-VC applications in high doses in combination with arsenic trioxide induce a potent cytotoxic oxidative stress in KRAS mutant cancer cells and their clinical relevance is yet to be determined by performing clinical trials." (PMID 38473779, 2024). "The RAS GTPases are the most frequently mutated oncogene family in human cancers with RAS isoforms (HRAS, KRAS, and NRAS) regulating critical intracellular signaling cascades that control cell proliferation and survival." (PMID 39379700, 2024). "Acquired KRAS alterations have been seen at the time of progression on trastuzumab in other cancer types." (PMID 38406801, 2024). "Targeted therapy and chemotherapy combined with immunotherapy are used more often in treating KRAS-induced cancers." (PMID 39252322, 2024). "The most commonly used immunotherapies for treating KRAS-related cancers are ICB, vaccination, and adoptive cell transfer (ACT)." (PMID 39252322, 2024). "A previous study from our laboratory uncovered a novel link between STAT3 and cancer showing that activation of STAT3 in KRAS mutant cancers led to the stabilization of epithelial differentiation." (PMID 38573819, 2024).
cancer (continued). "Building on the momentum of KRAS-specific cancer vaccines, a recent study introduced an innovative intranasal vaccine targeting NSCLC based on a mix of G12D mutant and wildtype KRAS peptides and enhanced by a nanoemulsion adjuvant." (PMID 38668053, 2024). "Taken together, these data suggest that YAP/TAZ activation is an early event when KRAS G12C–mutant cancer cells are exposed to KRAS G12C inhibitors and this activation is dynamically reversible in resistant cells." (PMID 39704172, 2024). "Here, we report that the Hedgehog signal is induced by KRASG12C inhibitors and mediates KRAS re-expression in cancer cells treated with a KRASG12C inhibitor." (PMID 38225225, 2024). "Future research should integrate genetic, immunological, and computational studies to unveil new therapeutic targets and refine treatment strategies for KRAS-mutant cancers." (PMID 39252322, 2024). "Taken together, these results, suggest that SUMOylation inhibition suppresses the growth of MYC-expressing KRAS-mutant cancer cells." (PMID 38992694, 2024). "In a clinical trial involving patients with RAS or RAF mutant cancers, including KRAS mutant NSCLC, the combination showed a mPFS of 6.35 months with manageable toxicity, suggesting potential efficacy across different KRAS mutation variants." (PMID 39199633, 2024). "Future work will be necessary to evaluate drug combination approaches and to extend our model to additional KRAS mutants and other KRAS-driven cancers." (PMID 39718828, 2024). "Studies showed that human epidermal growth factor receptor (HER), SHP-2, mammalian target of rapamycin (mTOR), and cyclin-dependent kinase 4/cyclin-dependent kinase 6 (CDK4/CDK6) inhibitors improved adagrasib efficacy in KRAS G12C-mutant cancers." (PMID 38397927, 2024). "KRAS alterations occur early in the carcinogenesis process and promote cancer cell survival, invasion, and migration." (PMID 38803537, 2024). "A potent cytotoxic oxidative stress induced by D-VC or L-VC in combination with ATO on KRAS mutant cancer cells has been reported." (PMID 38473779, 2024). "In this study, control group plasma was also examined for the KRAS gene for comparison with the cancer group plasma." (PMID 39673361, 2024). "The in-depth study of KRAS-specific mechanisms by which they enhance or hinder cancer proliferation will provide new insights for subsequent inhibitor development." (PMID 38763973, 2024). "For decades, efforts to target mutant KRAS, aptly nicknamed “the beating heart of cancer”, were unsuccessful." (PMID 38800401, 2024). "We found that composite mutations occur in 5% of cancer patients, mostly affecting the PIK3CA, EGFR, BRAF, and KRAS genes, which are common precision medicine targets." (PMID 38757376, 2024). "This study not only provides a strategy for developing drugs targeting "undruggable" proteins but also reveals that TKD is a promising therapeutic for treating KRAS-mutant cancers." (PMID 38937452, 2024). "In light of the successful genetic analysis of oncogenic point mutations in the KRAS, PIK3CA, and IDH1 genes of human cancer cell lines using RGEN-RFLP, it can be inferred that WD diagnosis should be possible by using this method." (PMID 39056796, 2024). "For instance, recent studies have revealed that increased ANGPTL4 expression is closely associated with the invasiveness and drug resistance of KRASG12D pancreatic cancer, and researchers have explored the mechanisms of drug resistance in KRAS-mutant cancers." (PMID 38992710, 2024). "KRAS mutations are highly prevalent in a wide range of lethal cancers, and these mutant forms of KRAS play a crucial role in driving cancer progression and conferring resistance to treatment." (PMID 38937452, 2024).